SSX3 (SSX family member 3)
Description:
Could act as a modulator of transcription.
Synonyms: CT5.3
Tractability: PROTAC: ubiquitination databases record sites on it.
Gene: Protein-coding gene on chromosome X (48,346,427 to 48,356,707, reverse strand). Ensembl gene ENSG00000165584.
Subcellular location (Human Protein Atlas): Nucleoli; Nucleoplasm
Gene Ontology:
Molecular function: protein binding
Biological process: regulation of DNA-templated transcription
Cellular component: nucleus
Homologues: Orthologues: chimpanzee SSX3 (96% identical), mouse Ssxb9 (34% identical), mouse Ssxb8 (33% identical), mouse Ssxb10 (32% identical), mouse Ssxb15 (32% identical), mouse Ssxb6 (32% identical), rat Ssx2 (32% identical), mouse Ssxb1 (32% identical), mouse Ssxb3 (32% identical), rat Ssx1 (32% identical), mouse Ssxb13 (31% identical), mouse Ssxb14 (30% identical), and 4 more. Paralogues in human: SSX2 (90% identical), SSX2B (90% identical), SSX7 (85% identical), SSX5 (85% identical), SSX4 (81% identical), SSX4B (81% identical), SSX1 (78% identical).
Diseases named in the same sentence as SSX3 in open-access papers:
SSX3 is named in the same sentence as 9 diseases in open-access papers, as found by Europe PMC text mining. Sharing a sentence is not in itself a finding about the gene and the disease. The quoted sentences say what the papers report.
breast cancer (3 papers, 2021 to 2023). A primary or metastatic malignant neoplasm involving the breast. "SSX3, the most stably expressed in “B” is a prognostic predictor for pancreatic ductal adenocarcinoma, while MAFK, the most variably expressed gene in “B”, appears responsible for the induction of breast cancer." (PMID 34209090, 2021).
melanoma (2 papers, 2014). A malignant, usually aggressive tumor composed of atypical, neoplastic melanocytes. "Interestingly SSX2 was detected in almost all melanoma tissues and derived cell lines (95%) compared to SSX4 (57%), SSX1 (38%), SSX5 (33%) and SSX3 (19%) expression." (PMID 24787708, 2014).
prostate carcinoma (2 papers, 2014 to 2016). A carcinoma that arises from epithelial cells of the prostate gland. "Prior work from our lab has demonstrated that treatment of human prostate cancer cell lines with epigenetic modifying agents (EMAs) can lead to expression of other SSX family members, including SSX3, SSX5, and SSX8." (PMID 27276714, 2016).
colon adenocarcinoma (1 paper, 2023). "The study examined the expression levels of the SSX1, SSX2, and SSX3 genes in NC and colon adenocarcinoma (COAD) tissue samples using RNA sequencing data from the TCGA repository (accessed on 20 February 2023)." (PMID 37241221, 2023).
leukemia (1 paper, 2023). A malignant (clonal) hematologic disorder, involving hematopoietic stem cells and characterized by the presence of primitive or atypical myeloid or lymphoid cells in the bone marrow and the blood. "This screening was conducted to determine the specificity of SSX1, SSX2, and SSX3 in additional cancer tissue samples, including leukemia in males and BC in females." (PMID 37241221, 2023).
cancer (4 papers, 2010 to 2023). A tumor composed of atypical neoplastic, often pleomorphic cells that invade other tissues. "To date, none of the 6 other HRneg/Tneg signature genes not functionally linked to chemokine pathways (PRRG3, RFX7, MATN1, SSX3, HRBL, and ZNF3) has shown any reported association with cancer." (PMID 20946665, 2010). "Moreover, we found two key TFs (EPO, ARID3A), four key PRSGs (CACNA1E, LINC01356, CGA and SSX3) and five key hallmarks of cancer gene sets (DNA repair, myc targets, E2F targets, mTORC1 signaling and unfolded protein response) in the regulatory network." (PMID 33816287, 2021). "SSX3, one of the cancer/testis antigens, is also a well-known oncogene in many tumors." (PMID 33816287, 2021). "Nonetheless, owing to the possibility of SSX3 gene expression in other cancer types, the gene was not eliminated from the gene screening." (PMID 37241221, 2023). "Interestingly, in region “B”, both the most stably expressed (SSX3) and the most unstably expressed (MAFK) genes have recognized roles in various forms of cancers." (PMID 34209090, 2021).
tumor (1 paper, 2010). "However, in contrast to SSX1/2, RT-PCR data from 44 SS tumor samples revealed that SSX3 was not a fusion partner with SS18." (PMID 20981248, 2010). "In this analysis they found that SSX1, 2, and 4 were expressed in 8%, 15%, and 15% of tumors, respectively, with no detection of SSX3 in any samples and detection of SSX5 in only 7 out of the total 325 tumor specimens evaluated." (PMID 20981248, 2010).
SSX3 also shares sentences with these, for which no sentence is quoted: Infertility (1 paper); pancreatic ductal adenocarcinoma (1).